IL9 (interleukin 9)
Diseases named in the same sentence as IL9 in open-access papers (continued):
Sharing a sentence is not in itself a finding about the gene and the disease.
asthma (continued). "Sialostatin L, a cysteine protease inhibitor from tick saliva, shows multifunctional effects on the immune system, which not only inhibits the percentage of CD4+ cells but also reduces the production of IL-9 from Th9 cells in an OVA-induced experimental asthma." (PMID 38444844, 2024). "Automated stratified exploratory data analysis also showed higher IL-9 values in controlled asthma in the subsets of allergen-sensitized patients and in those with low IL-17 values and higher NCR+ILC3 in uncontrolled asthma in children without allergen sensitization (tree/weed pollen)." (PMID 39685659, 2024). "IL-9 is associated with airway remodeling in the context of asthma, rather than lung inflammation or fibrosis." (PMID 38409078, 2024). "In addition, elevated mRNA expression levels of IL-9 and IL-9 receptor (IL-9R) were detected in patients with asthma." (PMID 39175819, 2024). "Medical treatments can thus be designed to target IL-5 and IL-9 to prevent asthma exacerbations." (PMID 39175819, 2024). "Although IL-9 plays an essential role in severe airway inflammation and bronchial hyper responsiveness in asthma and Respiratory Syncytial Virus (RSV) infection, the role of IL-9 is not yet identified in SARS-CoV-2 infection, and its associated immunopathology." (PMID 37429848, 2023). "Furthermore, expression of genes whose expression correlates with asthma, including Il9, Il4, Il13, Ccl11, Ccl24, and Muc5ac, was much lower in recipients of Id1 cKO Th9 cells." (PMID 37867222, 2023). "Trials of anti–IL-9 antibodies in asthma have been similarly disappointing." (PMID 37163370, 2023). "Interestingly, we observed elevated frequencies of IFNγ+IL-5+, IFNγ+IL-9+, and IFNγ+IL-13+ double-producing Tc cells, supporting type-2 skewing of IFNγ+ Tc1 cells in asthma." (PMID 37612281, 2023). "IL-6 is a cytokine that regulates cell growth and differentiation, immune response and its expression was related to metabolic dysfunction and asthma severity, IL-9 orchestrate inflammation that takes place in asthma while IL2RB is involved in T cell-mediated immune responses." (PMID 36143090, 2022). "In our study, serum levels of IL-9 were higher in obese asthma patients with respect to healthy controls and obese subjects, a finding that suggests that asthma and obesity might have additive effects on IL-9 secretion." (PMID 35807067, 2022). "Despite the evidence for the effect of IL-9 on mast cells in asthma, whether IL-9 affects the other effector cells in asthma remains unclear." (PMID 35524325, 2022). "Furthermore, anti-IL-9 treatment ameliorates airway inflammation in mouse models of asthma employing ovalbumin sensitization and challenge." (PMID 35524325, 2022). "In T2 asthma, the Th2 cytokines IL-4, IL-5, IL-9, IL-13, and IL-25, and the acute proinflammatory cytokines TNF-α, IL-1β, IL-6, and IL-8, subsequently lead to bronchial hyperresponsiveness (BHR), and plasma cells and antibody-producing cells secrete antibodies." (PMID 36430662, 2022). "Because asthma and allergic rhinitis have the same airway and the same disease, it is inferred that IL-9 may also play an important role in allergic rhinitis." (PMID 36172190, 2022). "Although increased expression of IL-9 has been shown to influence the activity of structural as well as eosinophils and mast cells in asthma, the influence of IL-9 on function of ILC2 and Th2 cells remains unclear." (PMID 35524325, 2022). "In addition, IL‐9 was reported as the most enriched gene in allergen‐specific T cells from patients with asthma." (PMID 35415925, 2022). "However, serum levels of the cytokines IL-4, IL-9, and IL-13 were reduced significantly (p < 0.01) in the evodiamine-treated group compared with the asthma group." (PMID 33577738, 2021). "Interestingly glucocorticoids, potent immune-suppressive agents that reduce cytokine expression by inhibiting transcription factors such as Activation Protein (AP)-1 and NF-κB, have been observed to reduce IL-9 expression in asthma patients." (PMID 34944921, 2021).
asthma (continued). "ILC2s could prevent the apoptosis of epithelial cells in subjects with sepsis through the secretion of IL-9, but whether ILC2-derived IL-9 plays an essential role in asthma remains unclear." (PMID 34177881, 2021). "Both IL-9 and IL-13 are Th2 cytokines that inhibit the proinflammatory response, but IL-9 promotes mast cell growth and function, and IL-13 mediates allergic inflammation and asthma." (PMID 34339269, 2021). "In particular, IL-13 plays a key role in asthma, allergy, fibrosis and other pathological processes sustained by eosinophils whereas IL-9, initially described as T cell growth factor, is a pleiotropic cytokine linked to tumor immunity, immunity to pathogens, allergy, and autoimmune disease." (PMID 33146828, 2021). "7P could dramatically suppress Th9 cell differentiation, suggesting that 7P may be a good candidate for reducing IL-9 production in asthma." (PMID 32258172, 2020). "MK2 and 3 are kinases activated by p38α; MK2/3 inhibitors or knockout of MK2/3 in mice reduced the production of IL-6 and IL-13 (two cytokines implicated in asthma) but not IL-5, IL-9 or GM-CSF in response to IL-33." (PMID 32103032, 2020). "Similar to observations found in murine studies, 7P diminished the differentiation of human naïve CD4+ T cells in peripheral blood to Th9 cells, further indicating that 7P may be a good candidate for reducing IL-9 production in asthma." (PMID 32258172, 2020). "IL-9 has various effects on numerous hematopoietic cells, which are central to asthma pathogenesis." (PMID 32258172, 2020). "IL-9 is a proallergic cytokine which plays a key role in asthma induction." (PMID 32770056, 2020). "Furthermore, IL-9 is an important factor in asthma pathogenesis, and anti-IL-9 antibody has been shown to treat asthma in phase II clinical trials." (PMID 32258172, 2020). "Lloyd and Harker reported that acetylation of histones mediates IL-9 expression in asthma." (PMID 32194547, 2020). "Th2 cytokines such as IL-4, IL-5, IL-13, and IL-9 also have the same effects on asthma." (PMID 31143692, 2019). "Application of sialostatin L almost completely abrogates airway hyperresponsiveness and eosinophilia in a model of experimental asthma and experimental data suggest its preventing effect in this disease model, probably by suppressing mast cell-derived IL-9 production by inhibiting IRF4." (PMID 31333488, 2019). "Though this cytokine has been known for three decades, for a long time IL-9 was mainly studied in the context of TH2-associated immuno-pathological conditions, since IL-9 played a role in asthma, IgE class switch recombination, and the resolution of parasitic infections." (PMID 31035677, 2019). "MEDI-528 targets IL-9 aiming to inhibit its function in the asthma pathogenesis." (PMID 31395084, 2019). "Th9 cells preferentially produce IL-9 and participate in allergic responses and asthma." (PMID 31776325, 2019). "Although chronic allergen exposure might increase IL-9 dependency in BHR development, the ineffectiveness of IL-9 neutralization therapy for asthma patients suggests that essential mediators of asthma pathogenesis other than IL-9 are produced by Th9 cells." (PMID 31216735, 2019). "In other AAD models, specifically in murine asthma, airway goblet cell hyperplasia was found to be directly induced by Th2-derived IL-9, whereas IL-4, IL-5, and IL-13 independently induce goblet cell hyperplasia, though indirectly via neutrophilic granulocytes." (PMID 30845208, 2019). "Since our in vitro data suggests a strong association of IL-9 and Foxo1, hence we speculated if Foxo1 also regulates IL-9 in vivo during the pathogenesis of asthma." (PMID 29867972, 2018). "Since Foxo1 inhibition in asthma model reduced IL-9-dependent inflammation and antitumor potential of Th9 cells, hence targeting Foxo1 could provide a potential therapeutic advantage in these diseases." (PMID 29867972, 2018). "Elevation of IL-4, IL-5, IL-9, and IL-13 was noted in asthma cytokine alterations." (PMID 30423980, 2018).
asthma (continued). "It is possible that IL-9 may play a crucial role in development of asthma, combining with Th17-related cytokines." (PMID 29138487, 2017). "Intranasal administration of anti-IL-9 antibody suppresses the severity of murine asthma." (PMID 28993609, 2017). "Similarly, Foxo1-inhibitor attenuated Ova-induced asthma (unpublished observations), IL-9 induction and PAS-positive goblet cells." (PMID 28993609, 2017). "However, IL-9 also contributes to pathology in inflammatory bowel disease and autoimmune diseases, in addition to asthma models, where it was shown to induce mucus production, goblet cell metaplasia, expression of IL-13 and airway hypersensitivity." (PMID 26936133, 2016). "Given the documented effects of IL-9 on asthma pathology, our findings suggest that defects in IL-9 production could be a critical part of Itk's effects on allergic asthma development." (PMID 26936133, 2016). "These reported observations support our hypothesis that targeting IL-9 via an anti-IL-9 mAb would be an effective treatment for patients with poorly controlled asthma." (PMID 24050312, 2013). "For example, both Th9 and Th17 are involved in asthma pathogenesis and produce IL-9." (PMID 24050312, 2013). "Currently, clinical data on anti-IL-9 therapeutics are modest and larger clinical trials are eagerly awaited to conclude whether this form of therapy can be used in the treatment of asthma." (PMID 24032029, 2013). "This is the largest double-blind, placebo-controlled, dose-ranging study performed to date to determine whether an anti-IL-9 monoclonal antibody has any clinical benefits in subjects with poorly controlled, moderate-to-severe asthma." (PMID 24050312, 2013). "It is still unclear whether the role of IL-9 is that of a dominant cytokine or one of a helper cytokine in asthma." (PMID 23671562, 2013). "In particular, inhibition of IL-9 has shown promising results in reducing allergic inflammation and mucus hypersecretion in mice and in clinical studies an IL-9 blocking antibody has been shown to reduce exercise-induced asthma." (PMID 23671562, 2013). "Interleukin (IL)-9, a multifunctional cytokine produced by type 2 T helper cells (Th2), lymphocytes, and mast cells, is proposed to be a central mediator in the pathogenesis of asthma." (PMID 24050312, 2013). "Taken together, evidence from these and other experimental studies indicated that targeting IL-9 may offer a novel approach to the treatment of asthma." (PMID 24050312, 2013). "Preclinical studies suggest that interleukin-9 may be a central mediator in the development and maintenance of airway inflammation in asthma." (PMID 24050312, 2013). "Importantly, these findings and other literature show a positive correlation between IL-9 and asthma pathogenesis." (PMID 23940740, 2013). "IL-9 demonstrates pro-inflammatory activity in several mouse models of inflammation and appears to play a significant role in the pathogenesis of atopic diseases and asthma." (PMID 22413008, 2012). "The potential of Th2 cells to promote allergic immunopathology is amplified by production of a range of mediators including IL-4, IL-5, IL-9, IL-13 and IL-25 which together promote the salient feature of asthma such as IgE production, AHR, inflammation and tissue remodelling." (PMID 19769993, 2010). "Animal data indicate that IL-9 can promote asthma through IL-13-independent pathways via expansion of mast cells, eosinophils, and B cells, and through induction of IL-13 production by hemopoietic cells for mucus production and recruitment of eosinophils by lung epithelial cells." (PMID 18315837, 2008). "Despite this, in an animal model of asthma the treatment with an anti-IL-9 antibody reduces airway inflammation and hyperresponsiveness suggesting that blockade of IL-9 may be a new therapeutic strategy for bronchial asthma." (PMID 18315837, 2008). "Evidence from both murine and human mapping studies shows that IL-9 is a candidate gene for asthma." (PMID 15823208, 2005).
asthma (continued). "We show that a single treatment with IL-33 and TL1A is sufficient for induction of IL-9-producing ILC2s in vivo and that endogenous IL-33 and TL1A are necessary for rapid induction of IL-9high ILC2s after a single exposure of naïve mice to A. alternata, a major asthma-associated allergen." (PMID 38597952, 2024). "Indeed, IL-9 is an important mediator in asthma, especially when administered intranasally." (PMID 38727220, 2024). "Future work could further investigate whether altered levels of IL-5 and IL-9 can be used as biomarkers of asthma development, and further explore the potential mechanism of action of IL-5 and IL-9 in asthma, and evaluate their potential for clinical prevention and treatment of asthma." (PMID 39175819, 2024). "The results show that asthma is significantly correlated with elevated levels of IL-5 and IL-9 [IL-5, odds ratio (OR) = 1.112, 95% confidence interval (CI): 1.009–1.224, P = 0.032; IL-9, OR = 1.111, 95% CI: 1.013–1.219, P = 0.025], and the results of IVW are also supported by Radial-MR." (PMID 39175819, 2024). "Interestingly, anti–IL-9 blocking antibodies inhibit allergic airway inflammation and hyperresponsiveness in mouse models and have been examined in clinical trials for treatment of humans with asthma." (PMID 38483511, 2024). "Finally, the automated stratified exploratory data analysis showed higher serum levels of IL-9 in children with controlled asthma at 12 months, both in the subsets of patients with sensitization to aeroallergens and in the subset of patients with initial IL-17 levels < 1.06 pg/mL." (PMID 39685659, 2024). "The results of the MR analysis did not support that increased IL-9 levels increased asthma risk." (PMID 39175819, 2024). "Moreover, IL-9 promotes mast cell growth in vitro, while neutralization of IL-9 markedly diminished mucosal mast cell activation and mast cell numbers in the lung in a mouse model of asthma." (PMID 35524325, 2022). "In addition to its well-established role in the pathogenesis of asthma and chronic inflammatory diseases, the role of IL-9 in the pathogenesis of inflammatory CNS diseases, including multiple sclerosis and experimental autoimmune encephalomyelitis (EAE), has been extensively studied." (PMID 36366333, 2022). "Moreover, it is noteworthy that IL-9 which is a Type II cytokine behaved differently from other Type II cytokines (IL-4, IL-5, and IL-13) and was associated with an increase in ACE2 expression in sputum of asthma patients." (PMID 35111161, 2021). "Th9 cells and IL-9 could promote activation and accumulation of MCs, T cells, type 2 innate lymphoid cells (ILC2s), and eosinophils concomitantly with increased levels of IgE, IL-13, and IL-5 in asthma models." (PMID 33748292, 2021). "Thus, the future of targeting IL-9 in asthma is unclear although it is still possible that this pathway may be a valid target for a subgroup of asthma patients." (PMID 31191511, 2019). "In regards to T lymphocytes, Th2 cells are considered one of the central players in asthma pathogenesis, as long as these cells participate in and coordinate the onset and progression of the inflammatory response in asthma through the release of cytokines, especially IL-4, IL-5, IL-9, and IL-13." (PMID 31019244, 2019). "Therefore, targeting IL-9 may be interesting in the hunt for newer and more specific asthma treatment strategies." (PMID 31395084, 2019). "Thus, whether inhibiting Itk or other TCR signalling components will be a useful therapeutic strategy for treating or preventing symptoms of asthma and other diseases in which IL-9 participates remains an important question." (PMID 26936133, 2016). "Moreover, in two randomized phase 2a trials carried out in subjects with mild-to-moderate asthma, the humanized anti-IL-9 monoclonal antibody MEDI-528 exhibited an acceptable safety profile and also evoked a trend toward improvement in asthma symptom scores and disease exacerbation rates." (PMID 23853765, 2013).
asthma (continued). "Thus, an important contribution of IL-9, in asthma, may instead be on epithelial integrity and ciliated cell number and function, leading to impaired mucus clearance, particularly in severe disease, something that can be said of IL-13 as well." (PMID 23671562, 2013). "Elevated IL-4, IL-9, and TNF-α were observed in non-T2 asthma compared with T2-high asthma, while children exhibited higher levels of IL-2, IL-6, IFN-γ, and IL-17A than adults." (PMID 41601686, 2026). "Very recently it has been described that IL-9 induction was restrained by IFN-γ/STAT1 and IL-10, pointing to a new role of this pathway in the modulation of asthma disease." (PMID 40650018, 2025). "For example, in a model of allergen-induced experimental asthma in ST2KO mice, deletion of ST2 led to elevated TSLP production which in turn stimulated the emergence of IL-9-producing ILC2 cells." (PMID 41465219, 2025). "IL-9, initially identified as a TH2-type cytokine with T-cell and mast-cell growth factor properties, has recently gained recognition for its role in asthma and allergies." (PMID 38337546, 2024). "IL-9–producing CD4+ T (Th9) cells induce allergies, such as asthma and atopic dermatitis, and inflammation/autoimmune diseases, such as inflammatory bowel diseases, multiple sclerosis, systemic lupus erythematosus, and psoriasis." (PMID 37909329, 2023). "The concomitant induction of DUSP8 and IL-9 in peripheral blood T cells of people with asthma and AD supports that DUSP8 induces IL-9 production." (PMID 37909329, 2023). "This study therefore aimed to elucidate the role of IL-9 on ILC2 and Th2 cells using a murine model of asthma." (PMID 35524325, 2022). "The present study further explored the role of IL-9 by comparing the differences in airway inflammation and percentages and numbers of target cells (ILC2 cells, Th2 cells and mast cells) in murine asthma models of WT and Il9−/−mice challenged with HDM." (PMID 35524325, 2022). "IL-9 level in lung tissue and BALF of asthma groups (n = 8 for each group) were significantly higher than the control groups (n = 8 for each group)." (PMID 36253857, 2022). "In different asthma models, the IL-2-STAT5 pathway is regulated by various factors including NO, TL1A, and Itk and contributes to induction of IL-9 and differentiation of Th9 cells." (PMID 33748292, 2021). "Lloyd and Harker also reported that acetylation of histones mediates IL-9 in asthma, and inhibition of H3K27 acetylation decreases the expression of IL-9." (PMID 32194547, 2020). "Therefore, inhibiting IL-9 production may be another potent avenue for treating asthma." (PMID 32258172, 2020). "In asthma, the paradigm of allergic disease, the cytokine profile in BAL shows elevation of IL-4, IL-5, and IL-9 compared to control groups." (PMID 31772507, 2019). "IL‐9, in combination with TGF‐β, can induce the development of Th17 cells which are found in the lungs of patients with severe asthma and in the skin of patients with chronic atopic dermatitis." (PMID 29164823, 2018). "IL-9 is over-expressed in BAL fluid and lung tissue in asthma patients and the quantity of Th9 cells directly correlated with AHR severity, whereas IL-9 neutralization relieves local inflammation." (PMID 28724400, 2017). "Higher expression of Th2-driven cytokines (IL-4, IL-5, IL-9, and IL-13), TSLP, IL-25 and IL-33 in nasal tissues was observed in severe asthma." (PMID 28199345, 2017). "The percentage of γδTCR+CD3+, IL-9+CD3+, IL-9+γδT lymphocytes was higher, whereas the percentage of IL-10+ CD3+ lymphocytes was lower in the asthma control group than in the normal control group (P < 0.001)." (PMID 27518187, 2016). "Asthma symptoms are related to the presence of activated Th2 cytokine-producing cells (IL4, IL5, IL9 and IL13) in the airway wall." (PMID 26986948, 2016).